LSM1 (LSM1 homolog, mRNA degradation associated)
Diseases named in the same sentence as LSM1 in open-access papers (continued):
Sharing a sentence is not in itself a finding about the gene and the disease.
epilepsy (1 paper, 2025). A brain disorder characterized by episodes of abnormally increased neuronal discharge resulting in transient episodes of sensory or motor neurological dysfunction, or psychic dysfunction. "In this work, we screened five key m7G regulators in epilepsy and created a nomogram based on them to predict the risk of epilepsy, including METTL1, NUDT3, EIF4E3, LSM1, and SNUPN." (PMID 40658715, 2025). "Gene expression analysis of datasets GSE143272 and GSE190452 identified 8 differentially expressed m7G regulators (NUDT3, EIF4E3, LARP1, IFIT5, SNUPN, METTL1, EIF4A1, and LSM1) in epilepsy." (PMID 40658715, 2025). "Thus, we planned to investigate LSM1’s functions in the development of epilepsy, particularly immunological epilepsy." (PMID 40658715, 2025). "The boxplot revealed that epilepsy patients had up-regulated expression levels of NUDT3, EIF4E3, LARP1, IFIT5, and SNUPN, and down-regulated expression levels of METTL1, EIF4A1, and LSM1." (PMID 40658715, 2025). "Patients with epilepsy were more likely to exhibit aberrant expression of SNUPN, LSM1, and IFIT5." (PMID 40658715, 2025).
glioblastoma (1 paper, 2023). The most malignant astrocytic tumor (WHO grade IV). "Despite these findings in other cancers, the precise role of LSM1 in glioblastoma remains largely unexplored." (PMID 37954131, 2023). "We firstly conducted the comparative analysis of LSM1 expression levels in glioblastoma (GBM) and normal brain tissues." (PMID 37954131, 2023). "The effects of LSM1 overexpression and knockdown on U87 glioblastoma (GBM) cells were further examined." (PMID 37954131, 2023).
head and neck squamous cell carcinoma (1 paper, 2024). A squamous cell carcinoma that arises from any of the following anatomic sites: lip and oral cavity, nasal cavity, paranasal sinuses, pharynx, larynx, and salivary glands. "Besides, knocking out LSM1 homolog (LSM1)/nucleoside diphosphate-linked moiety X-type motif 5 (NUDT5) can inhibit head and neck squamous cell carcinoma (HNSCC) cell invasion and migration by inhibiting N7-methylguanosine (m7G) modification." (PMID 38515628, 2024).
lobular breast cancer (1 paper, 2022). "The results showed that LSM1 mRNA levels were significantly higher in ductal breast cancer, invasive ductal breast cancer, lobular breast cancer and invasive lobular breast cancer compared to matched normal tissues." (PMID 35692083, 2022).
lymph node metastasis (1 paper, 2002). "The finding of high expression in LNCaP cells, which are derived from a lymph node metastasis, appears to contradict the conclusion of Lsm1 being a metastasis suppressor gene." (PMID 11953827, 2002).
lymphoma (1 paper, 2024). A malignant (clonal) proliferation of B- lymphocytes or T- lymphocytes which involves the lymph nodes, bone marrow and/or extranodal sites. "Future studies are required to investigate the specific functions of LSM1 further to understand its role in lymphomas better." (PMID 39417944, 2024).
Neurodevelopmental delay (1 paper, 2025). "A part of the Lsm1–7 complex, LSM1 is responsible for the degradation of mRNA in the cytoplasm, which, according to studies on neurodevelopmental delay, is being studied as a potential novel candidate gene for neurodevelopmental disorders." (PMID 40658715, 2025).
viral infection (1 paper, 2022). "Furthermore, a comparison of known LSM1 targets between the control and CaMV-infected samples showed that viral infection does not influence decapping of those endogenous targets, although we cannot exclude the possibility that other targets might be affected (Figure�4B)." (PMID 35511183, 2022).
tumor (22 papers, 2002 to 2025). "The study revealed that the high expression of the LSM1 gene is closely associated with tumor progression, particularly showing significant upregulation in DCIS and invasive tumor regions." (PMID 40867511, 2025). "•High LSM1 expression is linked to tumor energy metabolism, significantly impacting mitochondrial function and cellular respiration.•Metabolic genes in tumor-cell-enriched regions are associated with prognosis." (PMID 40867511, 2025). "The elevated expression of LSM1 was closely linked to tumor cell energy metabolism, including oxidative phosphorylation and the PI3K/AKT/mTOR signaling pathway, and significantly impacted mitochondrial function and cellular respiration." (PMID 40867511, 2025). "To this end, we investigated the association between LSM1 expression and tumour immune infiltration in different datasets by multi‐omics." (PMID 35692083, 2022). "We hypothesized that since the LSM1 cluster network was rich in cancer and inflammation/immune related pathways, their high expression levels in a variety of cancers may be associated with tumour immune infiltration." (PMID 35692083, 2022). "Future studies should incorporate mechanistic investigations to provide a comprehensive understanding of LSM1's role in modulating immune responses in the tumor microenvironment." (PMID 37954131, 2023). "Then, we assessed LSM1 expression according to different clinical stages, and we found that LSM1 expression was significantly increased in both tumour tissues and patients with advanced stages." (PMID 35692083, 2022). "Consistently, suppression of LSM1 expression results in tumor cell proliferation block with decreased G1-phase." (PMID 35646684, 2022). "We further evaluated the relationship between LSM1 and a variety of tumour‐infiltrating immune cells." (PMID 35692083, 2022). "We evaluated LSM1 detected in tumour tissues using a commercial breast tissue microarray (TMA) using immunohistochemistry." (PMID 35692083, 2022). "We comprehensively screened the LSM1 profiles of all tumours and used different algorithms to analyse the expression of each cancer type and correlate it with LSM1 expression levels." (PMID 35692083, 2022). "Collectively, these results suggested that LSM1 can act as a tumour enhancer via promoting the migration and invasion of BRCA cells." (PMID 35692083, 2022). "The LSM family has 13 members (LSM1~LSM14B) which were strongly associated with tumorigenesis and metastasis of several tumor types." (PMID 34638387, 2021). "We found that LSM1 expression was significantly correlated with tumor stages and related to a worse distant-metastasis survival rate." (PMID 34638387, 2021). "LSM1 expression showed a significant positive correlation with tumor purity (r = 0.112, p = 3.96 × 10−4)." (PMID 34638387, 2021). "Beyond the LSm1 correlates, relatively little remains known about the role for CaSm in the process of neoplastic transformation or how its downregulation in the setting of established neoplasia leads to decreased tumor growth." (PMID 26751936, 2016). "The transfectant #14-1 showed lymph node metastases (three out of five mice) and marked reduction of Lsm1 gene expression in these metastatic foci and the primary tumours (implantation site) on in situ hybridization." (PMID 11953827, 2002). "M2-type macrophages were notably increased in tumor regions with high LSM1 expression, suggesting that LSM1 may promote the formation of an immunosuppressive TME by regulating macrophage polarization and function." (PMID 40867511, 2025). "Furthermore, by using ST, the study demonstrated significant overexpression of metabolism-related genes (e.g., HK2, PDHA1, and CS) in tumor regions, further supporting the critical role of LSM1 in regulating tumor energy metabolism." (PMID 40867511, 2025). "The upregulation of LSM1 in GBM may contribute to dysregulated RNA metabolism and altered gene expression patterns associated with tumor progression." (PMID 37954131, 2023).
tumor (continued). "Similarly, highly expressed LSM1 was also reported to promote tumor cell growth in epithelial tissues, contributing to the transformed state." (PMID 36761423, 2022). "The H‐score of LSM1 increased significantly with tumour progression." (PMID 35692083, 2022). "We found that BRCA tumour samples had the next highest frequency of LSM1 genetic alterations." (PMID 35692083, 2022). "We observed the gene expression levels of LSM1 master regulators in each tumour." (PMID 35692083, 2022). "Similarly, in LUSC, higher expression of AGO2, EIF3D, and LSM1 were positively correlated with tumor stem cell score but negatively correlated with immune infiltration degrees, indicating a poor prognosis." (PMID 36226166, 2022). "Overexpression of LSM1 may play a role in pre‐mRNA splicing by mediating U4/U6 snRNP formation, affecting cell metabolism, cell cycle and destabilization of certain tumour suppressor transcripts in multiple ways, leading to cellular oncogenesis." (PMID 35692083, 2022). "We then investigated the genetic alterations of LSM1 in various tumour types in the TCGA dataset." (PMID 35692083, 2022). "In addition, 11 tumor-specific exonic variants were identified in six genes spanning the 8p11-p12 genomic region (RAB11FIP1, GPR124, ADAM2, LSM1, TACC1, ZNF703)." (PMID 29844878, 2018). "Additionally, the study found a positive correlation between LSM1 expression and macrophage markers CD163 and CXCR4, indicating that LSM1 may influence tumor immune evasion and progression by modulating macrophage infiltration and activity." (PMID 40867511, 2025). "Besides, LSM1 is related to immune cell infiltration in tumor discovery." (PMID 40658715, 2025). "Our exploration also delved into LSM1's involvement in immune cell infiltration in GBM, revealing intriguing correlations that suggest its role in shaping the tumor microenvironment and influencing immune responses." (PMID 37954131, 2023). "The findings of this study demonstrate the upregulation of LSM1 in GBM and its contribution to tumor progression by enhancing cell proliferation, invasion, and influencing immune cell infiltration." (PMID 37954131, 2023). "We also analysed the sensitivity and specificity of LSM1 in BRCA, and the results show the percentage of tumour samples showing higher expression of the selected gene than normal samples at each major cut‐off value." (PMID 35692083, 2022). "More than half of the m7G-related genes were significantly upregulated in tumor samples, such as METTL1, WDR4, EIF4E, LARP1, and LSM1." (PMID 36761423, 2022). "Next, we examined the mRNA expression of LSM1 in 30 paired BRCA and non‐tumour tissues from Taiwan biobank." (PMID 35692083, 2022). "Overall, the findings suggest that LSM1 expression in GBM is associated with specific immune cell infiltration patterns, which provides insights into the potential immunoregulatory role of LSM1 in GBM, highlighting its involvement in modulating the tumor microenvironment and immune cell responses." (PMID 37954131, 2023). "The upregulation of LSM1 alters the expression of genes critical mediators of apoptosis, metastasis and epithelial mesenchymal transition (EMT), which complements the proposed function of LSM1 in mRNA regulation and provides a putative mechanism for LSM1‐mediated tumour progression." (PMID 35692083, 2022). "Statistical analysis revealed increased expression of FGFR1 neighboring genes on the 8p12 amplicon (BAG4, LSM1 and WHSC1L1) in FGFR1 amplified tumours, suggesting a broad rather than focal amplicon and raises the potential for codependencies." (PMID 26905262, 2016).
cancer (19 papers, 2002 to 2025). A tumor composed of atypical neoplastic, often pleomorphic cells that invade other tissues. "Similar associations have been observed in other cancers, further supporting LSM1 as a prognostic marker." (PMID 37954131, 2023). "We analysed the effect of LSM1 mutations on immune cell infiltration in various cancer types and the effect of immune cell type in pan‐cancer by mutation module." (PMID 35692083, 2022). "We investigated mutations of LSM genes in BRCA patients from TCGA Pan-Cancer Atlas (n = 1082 patients) in the cBioPortal platform, and found surprisingly high rates of alterations in LSM1 (25%), LSM2 (11%) LSM4 (8%), and LSM14B (23%)." (PMID 34638387, 2021). "Lsm1 was first isolated from human pancreatic cancers as an up-regulated gene and termed cancer-associated Sm-like protein (Casm)." (PMID 11953827, 2002). "We found that the LSM1 gene was mutated in up to 12% of all cancers." (PMID 35692083, 2022). "Similar prognostic significance of LSM1 has been observed in other cancers, where elevated LSM1 expression is correlated with reduced overall survival and disease-free survival." (PMID 37954131, 2023). "LSM1 mRNA expression also correlated significantly with cancer stage, with patients with advanced cancer tending to express higher LSM1 mRNA expression." (PMID 35692083, 2022). "Correlation analysis demonstrated that the expression of m7G regulators was positively correlated with their CNV alterations, especially LSM1 in most cancers, whereas the correlation of most m7G regulators in THCA showed weakly." (PMID 36339001, 2022). "Although the role of Like-Sm 1 (LSM1), a component of the mRNA splicing machinery, has been studied in various cancers, its significance in GBM remains unclear." (PMID 37954131, 2023). "Thus, LSM1 was found to be an important gene in maintaining the transformation phenotype of cancer cell lines." (PMID 35692083, 2022). "Some of these genes have been previously identified as playing a role in tumorigenesis or cancer progression including, WHSC1L1, CLTC, HSF1, and LSM1." (PMID 22719901, 2012). "Mechanistically, LSM1 has been shown to interact with various proteins involved in cell cycle regulation, apoptosis, and epithelial-mesenchymal transition (EMT), emphasizing its multifaceted involvement in cancer progression." (PMID 37954131, 2023). "These potential alternative driver alterations were found to affect known cancer genes, including amplification of PIK3CA or MYC, and likely driver genes mapping to the 8p11-p12 amplicon, including ZNF703, RAB11FIP1, LSM1, PPAPDC1B, WHSC1L1 and FGFR1." (PMID 25994018, 2015). "Remarkably, the P-body components LSM1 and PAT1 remain highly connected to this cancer-specific network, raising the possibility that P-body disruption could have therapeutic value through selective killing of CIN cancers." (PMID 23390603, 2013). "The expression levels of LSM1-7, SNRPD1-3, SNRPB, SNRPF, SNRPG, SNRPE, and SNRPN were compared between cancer and non-cancer liver tissues in HCC patients from the TCGA and ICGC cohorts." (PMID 35281269, 2022).
infection (5 papers, 2007 to 2026). The state of being infected such as from the introduction of a foreign agent such as serum, vaccine, antigenic substance or organism. "First, viral P6 suppresses the DRB4/DCL4 node of PTGS, a process that seems to also function in lsm1 and dcp5 judging from the comparably reduced levels of tasiRNAs along de-repression of their targets during infection." (PMID 35511183, 2022). "First, we performed polysomal fractionation of CaMV-infected Col-0, lsm1 and dcp5 samples from three independent infection experiments." (PMID 35511183, 2022). "In HBV replication and infection models, siRNA-mediated knockdown of LSm1 increased all viral RNAs." (PMID 36016928, 2022). "The rdr2, rdr6 and dcl234 alleles exhibited comparable fresh weight loss to Col-0 during CM1841 infection, and it is noteworthy that the RNA silencing mutants did not reverse the developmental phenotypes of lsm1 and dcp5." (PMID 35511183, 2022). "Moreover, the lsm1Δ/Δ cells displayed the defects in hyphal development, biofilm formation, and host cell interaction, and exhibited the attenuated virulence in a murine infection model." (PMID 42075169, 2026).
neurodevelopmental disorder (2 papers, 2025). A behavioral and cognitive disorder with onset during the developmental period that involves impaired or aberrant development of intellectual, motor, or social functions. "Among them, HNRNPH2 and LSM1 have been implicated to be associated with various neurodevelopmental disorders in numerous studies." (PMID 40288647, 2025).
LSM1 also shares sentences with these, for which no sentence is quoted: Salmonella Infections (2 papers); small cell lung carcinoma (2); acute pancreatitis (1); adenoid cystic carcinoma (1); Cachexia (1); cervical carcinoma (1); colon cancer (1); esophageal carcinoma (1); gastric cancer (1); Lewy body disease (1); lung adenocarcinoma (1); Lynch syndrome (1); melanoma (1); mesothelioma (1); metastatic disease (1); Obesity (1); pancreatic adenocarcinoma (1); stomach adenocarcinoma (1); uterine corpus endometrial carcinoma (1).